FUS (FUS RNA binding protein)
Diseases named in the same sentence as FUS in open-access papers (continued):
Sharing a sentence is not in itself a finding about the gene and the disease.
amyotrophic lateral sclerosis (continued). "This means that this variant in HRNR occurs 1 in 300 Europeans, while other known pathogenic gene variants such as the Gly2019Ser variant of LRRK2 in PD (1 in 2,400 Europeans) or the Arg521Cys variant of FUS in amyotrophic lateral sclerosis (1 in 25,000 Europeans) are much less frequent." (PMID 35246273, 2022). "Mutated FUS has been linked to frontotemporal dementia and amyotrophic lateral sclerosis (ALS)." (PMID 33802132, 2021). "In 2018, BS was used to evaluate abnormal FUS protein-mediated stress granule formation which may be an underlying cause of amyotrophic lateral sclerosis (ALS)." (PMID 34360822, 2021). "Aberrant activity and localization of two RBPs, TDP-43 and FUS RNA binding protein (FUS), are implicated as the pathogenicity of amyotrophic lateral sclerosis (ALS) and frontotemporal dementia (FTD), two fatal neurodegenerative disorders that share clinical, genetic, and pathologic hallmarks." (PMID 32188117, 2020). "Mutations in FUS (fused in sarcoma) cause amyotrophic lateral sclerosis (ALS)." (PMID 31316445, 2019). "Mutations in coding and non-coding regions of FUS cause amyotrophic lateral sclerosis (ALS)." (PMID 30747709, 2019). "Like other proteins of the FET family (FUS, EWSR1 and TAF15; Ewing’s sarcoma (EWS) and TAF15 (TATA-binding protein-associated factor), mutations in fused in sarcoma (FUS) are directly linked with protein aggregation in amyotrophic lateral sclerosis (ALS) and frontotemporal dementia patients." (PMID 31238957, 2019). "The utility of the protocol was demonstrated on cell cultures from zebrafish that transgenically express disease-causing variants of human fused in sarcoma (FUS) and ataxin-3 proteins, in order to study amyotrophic lateral sclerosis (ALS) and spinocerebellar ataxia type-3 (SCA3), respectively." (PMID 30190267, 2018). "In the context of this review, it should be mentioned that FUS mutations have been found in patients affected by Amyotrophic Lateral Sclerosis (ALS), and Fronto-Temporal Lobar Degeneration (FTLD), two related yet distinct neurodegenerative disorders, and more recently in Essential Tremor (ET)." (PMID 26437437, 2015). "Genomic variants in TDP-43 and FUS, genes that encode stress granule proteins, were found to cause familial Amyotrophic lateral sclerosis and several other stress granule proteins (TIA-1, G3BP) may also be pathogenic." (PMID 24586208, 2014). "Splicing alternations were also reported to occur early on in Alzheimer's disease (AD), and failed nuclear transport and fibril formation by splicing factors harboring prion-like domains, such as hnRNP A/B and FUS was recently implicated in Amyotrophic Lateral Sclerosis (ALS)." (PMID 24651478, 2014). "The RNA-binding protein FUS is commonly mutated in familial cases of amyotrophic lateral sclerosis (ALS-FUS), where it forms cytoplasmic inclusions." (PMID 41832182, 2026). "Mutations in an RNA-binding protein FUS are known to cause familial amyotrophic lateral sclerosis (ALS)." (PMID 42187823, 2026). "Mutations and augmented expression in fused in sarcoma (FUS) can result in amyotrophic lateral sclerosis (ALS) and frontotemporal lobar degeneration (FTLD)." (PMID 41773017, 2026). "Next, we examined the in vitro condensation of FUS, an RNA binding protein implicated in amyotrophic lateral sclerosis (ALS) and frontotemporal dementia (FTD), and one of the most-studied proteins in condensation research." (PMID 41266615, 2026). "We tend to favor the model describing the liquid droplets of the RNA-binding protein FUS, which is a risk factor for amyotrophic lateral sclerosis (ALS)." (PMID 40503182, 2025). "Among them, TDP43, FUS, and hnRNPA2B1 represent molecular hallmarks of amyotrophic lateral sclerosis (ALS), where these RBPs are known for nuclear loss of function, aggregation tendency, and stress granules assembly." (PMID 40103230, 2025).
amyotrophic lateral sclerosis (continued). "FUS is a DNA/RNA‐binding protein implicated in the progression of amyotrophic lateral sclerosis and frontotemporal dementia (ALS/FTD)." (PMID 40448612, 2025). "Formation of cytoplasmic inclusions (CIs) of TDP-43 and FUS, along with DNA damage accumulation, is a hallmark of affected motor neurons in Amyotrophic Lateral Sclerosis (ALS)." (PMID 40437235, 2025). "FUS is an RNA-binding protein that has been linked to diverse neurodegenerative diseases including amyotrophic lateral sclerosis (ALS)." (PMID 40606579, 2025). "Amyotrophic lateral sclerosis (ALS) is a neurodegenerative disease targeting motor neurons, and mutations in the gene encoding SOD1, as well as TDP-43 and FUS protein aggregates, have been reported to play a role in the development of ALS." (PMID 40549339, 2025). "Fused in sarcoma (FUS) is an RNA-binding protein implicated in juvenile amyotrophic lateral sclerosis (ALS)." (PMID 40659544, 2025). "Tau aggregates condensation via LLPS is similar to amyotrophic lateral sclerosis (ALS)-associated protein aggregates of Fused in Sarcoma (FUS), hnRNPA1, and TAR DNA-binding protein 43 (TDP43)." (PMID 39596399, 2024). "The fused in sarcoma (FUS) protein is a hallmark of neurodegenerative diseases, such as amyotrophic lateral sclerosis (ALS) and frontotemporal dementia (FTD), in which phosphorylation of FUS impairs its aggregation tendency and prion-like characteristics." (PMID 39113127, 2024). "Aberrant condensation and localization of the RNA-binding protein (RBP) fused in sarcoma (FUS) occur in variants of amyotrophic lateral sclerosis (ALS) and frontotemporal dementia (FTD)." (PMID 38692734, 2024). "Various MN diseases, such as spinal muscular atrophy and amyotrophic lateral sclerosis (ALS), are thought to be caused in part by dysfunction of RNA-binding proteins (RBPs) including fused in sarcoma (FUS) and TAR DNA–binding protein 43kDa (TDP-43)." (PMID 39226364, 2024). "On the other hand, mutations or dysfunction of TDP43 and FUS are associated with widespread splicing misregulation, which leads to neurodegenerative disorders such as amyotrophic lateral sclerosis (ALS) and frontotemporal lobar degeneration (FTLD)." (PMID 39764514, 2024). "Amyotrophic lateral sclerosis (ALS) is a degenerative condition affecting the motor neurones, characterized by a multifaceted genetic makeup—mutations in genes such as SOD1, C9orf72, TARDBP, and FUS cause ALS." (PMID 39759457, 2024). "Irreversible mutations of many RNA binding proteins can contribute to degenerative diseases, such as mutations of TDP-43, hnRNPA1, and FUS in amyotrophic lateral sclerosis/frontotemporal dementia (ALS/FTD)." (PMID 37464880, 2023). "Mutations in the FUS gene are indeed linked to the pathogenesis of Amyotrophic Lateral Sclerosis (ALS), a neuronal disorder characterized by progressive motor neuron (MN) degeneration that ultimately leads to fatal paralysis." (PMID 36834591, 2023). "TAR DNA-binding protein 43 (TDP-43) and Fused in Sarcoma/Translocated in Sarcoma (FUS) are ribonucleoproteins associated with pathogenesis of amyotrophic lateral sclerosis (ALS) and frontotemporal lobar degeneration (FTLD)." (PMID 38111057, 2023). "Several RBPs, including FUS, are mutated or aggregated in amyotrophic lateral sclerosis (ALS), a neurodegenerative disease primarily caused by the death of motor neurons (MNs)." (PMID 36702823, 2023). "Amyotrophic lateral sclerosis (ALS) linked mutant FUS induce ER stress, and overexpression of mutant FUS colocalized with calreticulin (as a marker of ER) in NSC-34 motor neuron cells." (PMID 36875699, 2023). "Mutations in the RNA-binding protein FUS are linked to amyotrophic lateral sclerosis and frontotemporal dementia (ALS/FTD)." (PMID 37746061, 2023). "Variants in the ubiquitously expressed DNA/RNA-binding protein FUS cause aggressive juvenile forms of amyotrophic lateral sclerosis (ALS)." (PMID 37772684, 2023).
amyotrophic lateral sclerosis (continued). "We have been involved in analyses of the roles of G4-containing RNAs recognized by two G4-RNA-binding proteins, TDP-43 and FUS, which both are the amyotrophic lateral sclerosis (ALS) causative gene products." (PMID 35898304, 2022). "Amyotrophic Lateral Sclerosis (ALS) familial mutations in the FUS protein impede the self-regulation of NMD, which leads to excessive targeting of cellular transcripts." (PMID 35406756, 2022). "One of the major genes implicated in familial amyotrophic lateral sclerosis (ALS) is fused in sarcoma (FUS), a DNA/RNA binding protein, and multiple mutations in FUS have been identified." (PMID 34489731, 2021). "The interest in this protein has dramatically increased since a causative link was demonstrated between heritable and de novo FUS mutations and the dominant form of amyotrophic lateral sclerosis (ALS)." (PMID 34299185, 2021). "Intriguingly, mutations in the fused in sarcoma (FUS) gene, which are linked to amyotrophic lateral sclerosis (ALS), cause ER stress and the Drosophila FUS orthologue cabeza genetically interacts with Xrp1." (PMID 34871307, 2021). "Mutations in FUS, an RNA-binding protein involved in multiple steps of RNA metabolism, are associated with the most severe forms of amyotrophic lateral sclerosis (ALS)." (PMID 34488813, 2021). "The importance of FUS for cell homeostasis is underscored by the fact that variations in the gene encoding FUS have been causatively linked to the development of severe neurodegenerative diseases, particularly amyotrophic lateral sclerosis (ALS)." (PMID 34026839, 2021). "The identification of FUS mutations in familial and sporadic forms of amyotrophic lateral sclerosis (ALS) and frontotemporal lobar degeneration (FTLD) patients suggests that modifications in RNA metabolism might be an essential event in the disease pathogenesis." (PMID 34299185, 2021). "Analysis of RBM20 RNA binding by eCLIP reveals a gain-of-function preference of mutant RBM20 for 3′ UTR sequences that are shared with amyotrophic lateral sclerosis (ALS) and processing-body associated RNA binding proteins (FUS, DDX6)." (PMID 34732726, 2021). "Mutations in FUS that are associated with amyotrophic lateral sclerosis (ALS) were found to dysregulate SMN function, leading to loss of snRNA levels and affected splicing patterns." (PMID 34065983, 2021). "Mutations in the Fused in Sarcoma (FUS) RNA-binding protein have been linked to the fatal neurodegenerative disease amyotrophic lateral sclerosis (ALS), as they cause approximately 5% of the cases for familial ALS and 1% of sporadic ALS1." (PMID 33580145, 2021). "FUS is a nucleic acid binding protein that, when mutated, cause a subset of familial amyotrophic lateral sclerosis (ALS)." (PMID 32276960, 2020). "For instance, the identification of a liquid-to-solid-phase transition with disease-associated FUS mutations led to the recognition of aberrant phase separation as a major contributing factor in amyotrophic lateral sclerosis (ALS)." (PMID 31217303, 2019). "Mutations in Fused in Sarcoma (FUS or TLS) are the fourth most prevalent in Western European familial amyotrophic lateral sclerosis (ALS) populations and have been associated with causing both early and very late disease onset." (PMID 31682085, 2019). "Mutations in FUS have been linked to familial amyotrophic lateral sclerosis (ALS), with brains of affected patients demonstrating FUS-positive inclusions in the cytoplasm of degenerating neurons and glia as well as decreased levels of nuclear FUS." (PMID 30081499, 2018). "Another good example is FUS, a nuclear RNA-binding protein, splicing regulator and circRNA biogenesis factor, which is also mutated in familial amyotrophic lateral sclerosis (ALS)." (PMID 29116363, 2018).
amyotrophic lateral sclerosis (continued). "We found that FUS, an oscillating expressed nuclear protein implicated in the pathogenesis of amyotrophic lateral sclerosis (ALS) and frontotemporal dementia (FTD), exerted a novel feedback route to regulate circadian gene expression." (PMID 30338063, 2018). "An aberrant liquid-to-solid phase transition, observed in in vitro reconstituted droplets of FUS protein, has been recently proposed as a possible pathogenic mechanism for amyotrophic lateral sclerosis (ALS)." (PMID 30272018, 2018). "Evidence suggests that cytoplasmic mislocalization of nuclear proteins such as transactive response DNA-binding protein 43 (TDP-43) and fused in sarcoma (FUS) may be associated with neurotoxicity in amyotrophic lateral sclerosis (ALS) and frontotemporal lobar degeneration." (PMID 28453527, 2017). "Mutations in fused in sarcoma (FUS), a DNA/RNA binding protein, are associated with familial amyotrophic lateral sclerosis (ALS)." (PMID 28094300, 2017). "The RNA binding protein FUS functions in several RNA biosynthetic processes and has been linked to the pathogenesis of amyotrophic lateral sclerosis (ALS)." (PMID 28358055, 2017). "The RNA-binding protein FUS participates in several RNA biosynthetic processes and has been linked to the pathogenesis of amyotrophic lateral sclerosis (ALS) and frontotemporal dementia." (PMID 28358055, 2017). "FUS (Fused-in-sarcoma), one of causative genes for familial amyotrophic lateral sclerosis/frontotemporal dementia (ALS/FTD), encodes a multifunctional DNA/RNA binding protein." (PMID 27731383, 2016). "Mutations within the FUS gene (Fused in Sarcoma) are known to cause Amyotrophic Lateral Sclerosis (ALS), a neurodegenerative disease affecting upper and lower motoneurons." (PMID 28082870, 2016). "Additional gene regulation is provided by RNA/DNA handling proteins, notably TDP-43 and FUS, mutations of which have been linked to pathogenesis in some cases of amyotrophic lateral sclerosis (ALS)." (PMID 27906075, 2016). "FUS (Fused-in-Sarcoma) is a multifunctional DNA/RNA binding protein linked to familial amyotrophic lateral sclerosis/frontotemporal dementia (ALS/FTD)." (PMID 27731383, 2016). "Mutations in the fused in sarcoma (FUS) gene have been linked to amyotrophic lateral sclerosis (ALS)." (PMID 26795035, 2016). "Fused in sarcoma (FUS) is an RNA-binding protein associated with the neurodegenerative diseases amyotrophic lateral sclerosis (ALS) and frontotemporal lobar degeneration." (PMID 27793099, 2016). "Mutations in other domains of the FUS protein are known to cause amyotrophic lateral sclerosis (ALS) and frontotemporal dementia (FTD)." (PMID 27395408, 2016). "Fused in sarcoma (FUS) mutations on chromosome 16 have in recent years been recognised as a relatively rare, yet important cause of amyotrophic lateral sclerosis (ALS)." (PMID 26452761, 2015). "For example, mutations in TAR DNA binding protein (TARDBP; OMIM*605078) and FUS cause familial amyotrophic lateral sclerosis (ALS)." (PMID 25375143, 2014). "The gene encoding a DNA/RNA binding protein FUS/TLS is frequently mutated in amyotrophic lateral sclerosis (ALS)." (PMID 24204307, 2013). "Mutations in the gene encoding the RNA-binding protein fused in sarcoma (FUS) can cause familial and sporadic amyotrophic lateral sclerosis (ALS) and rarely frontotemproal dementia (FTD)." (PMID 23046583, 2012). "Mutations in the SOD1, TARDBP, and FUS genes have been commonly identified in Amyotrophic Lateral Sclerosis (ALS)." (PMID 21829392, 2011). "Recently identified mutations in TDP-43 and FUS, both RNA-binding proteins, have been shown to cause the neuro­degenerative disorder amyotrophic lateral sclerosis (ALS)." (PMID 21915392, 2011). "In a small number of amyotrophic lateral sclerosis patients, we identify rare coding variants in the HNRNPUL1 gene, which alter the ability of hnRNPUL1 to bind nucleotides, RNAs, and FUS." (PMID 41971996, 2026).
amyotrophic lateral sclerosis (continued). "FUS is an RNA-binding protein known to mislocalize to the cytoplasm in amyotrophic lateral sclerosis (ALS) and frontotemporal dementia (FTD)." (PMID 41282267, 2025). "Mutations in the FUS gene cause aggressive amyotrophic lateral sclerosis (ALS-FUS)." (PMID 40700505, 2025). "Mutations in FUS and TARDBP cause amyotrophic lateral sclerosis (ALS), but the precise mechanisms of selective motor neuron degeneration remain unresolved." (PMID 40389397, 2025). "In neurodegenerative diseases like amyotrophic lateral sclerosis (ALS), mutations in RNA-binding proteins such as TDP-43 and FUS impair splicing and RNA transport, causing widespread neuronal dysfunction." (PMID 39940824, 2025). "Moreover, Hdj1 has been shown to interact with FUS, a pathogenic protein in the neurodegenerative disease amyotrophic lateral sclerosis (ALS), driving and stabilizing LLPS condensates even under highly dynamic conditions." (PMID 40985478, 2025). "Sarcomeric fusion protein (FUS) is an RNA-binding protein closely related to neurodegenerative diseases such as amyotrophic lateral sclerosis (ALS)." (PMID 41322492, 2025). "RNA-binding proteins with low-complexity domains (LCDs), such as FUS and TDP-43, are particularly prone to aggregation and are linked to neuromuscular disorders like amyotrophic lateral sclerosis (ALS)." (PMID 39941124, 2025). "Fusion sarcoma (FUS), a ubiquitously expressed RBP, whose lysine acetylation in the RRM reduces RNA binding to FUS and reduces cytoplasmic inclusion body formation, has been associated with familial amyotrophic lateral sclerosis (ALS) and frontotemporal dementia (FTD) development." (PMID 39518890, 2024). "The proteins implicated in amyotrophic lateral sclerosis (ALS), including TAR DNA-binding protein 43 (TDP-43), fused in sarcoma (FUS), superoxide dismutase 1 (SOD1), and chromosome 9 open reading frame 72 (C9orf72) repeat peptides, are also related to the DDR." (PMID 39063148, 2024). "We comparethe behavior of three different protein condensates, i.e., those formedby either hnRNPA1, FUS, or TDP-43 proteins, whose liquid-to-gel transitionsare associated with the onset of amyotrophic lateral sclerosis andfrontotemporal dementia." (PMID 37194953, 2023). "For instance, exosomal superoxide dismutase 1 (SOD1), exosomal dipeptide-repeat proteins (DPRs), exosomal TAR DNA-binding protein (TARDBP), and fused in sarcoma (FUS) have all been found to affect the spread of amyotrophic lateral sclerosis." (PMID 36834471, 2023). "For instance, arginine methylation of FUS regulates its interaction with the nuclear import carrier Transportin and might be a therapeutic target for familial amyotrophic lateral sclerosis (ALS) caused by FUS mutations." (PMID 37442236, 2023). "Here, we establish that HtrA1 inhibits the aggregation of α-syn as well as FUS and TDP-43, which are implicated in amyotrophic lateral sclerosis (ALS) and frontotemporal dementia (FTD)." (PMID 37674720, 2023). "FUS mutations have been linked to amyotrophic lateral sclerosis (ALS) and frontotemporal lobar dementia (FTLD) in which pathological FUS inclusions cause neuronal degeneration." (PMID 37123224, 2023). "In certain neurodegenerative diseases, amyotrophic lateral sclerosis and frontotemporal dementia, FUS irreversibly condenses into solid-like cytoplasmic aggregates, suggesting a connection between material properties and the extent of nuclear depletion." (PMID 36163138, 2022). "FUS and TDP43 (RGG-motif containing nuclear proteins involved in Amyotrophic Lateral Sclerosis) are reported to accumulate mutations that lead to the formation of cytoplasmic amyloid inclusions which are linked to the disease." (PMID 35440550, 2022). "Interestingly, a recent study showed that TDP-43 and FUS, associated with amyotrophic lateral sclerosis (ALS), are abundant in paraspeckles and interact directly with NEAT1_2 in ALS-patient-derived motor neurons." (PMID 35805146, 2022).